IGF1 (insulin like growth factor 1)
Diseases named in the same sentence as IGF1 in open-access papers (continued):
Sharing a sentence is not in itself a finding about the gene and the disease.
cancer (continued). "According to our results, IGF-1 and IGF-1R can serve as a valuable prognostic biomarker in some cancer types." (PMID 34804946, 2021). "As a result, the activation of IGF-1/IGF-1R is further inhibited, which indirectly leads to an antiproliferative effect in cancer cells." (PMID 34208601, 2021). "Fractionated radiation induces an increase in IGF1 secretion level and gradually up-regulates IGF1R expression in cancer stem cells (GSCs)." (PMID 34178997, 2021). "The releases of integrins, insulin-like growth factor-1 (IGF-1), VEGF, MMP, PDGF, and help to facilitate cancer cell extravasation." (PMID 33546106, 2021). "Based on previous researches, miR-98-5p is available to regulate cancer development through various target genes, like XIAP, BZW1, STAT3, IGF1 and so on." (PMID 34895048, 2021). "IGF-1 and EGF are known to be overexpressed in most types of cancer tissues and contribute to cancer resistance to existing treatments." (PMID 35008759, 2021). "In addition, we found that acetylation of H2A.Z in HCC could change the chromatin status and promote the transcription of downstream genes, including TCF3, CDK14, JUP, SPINT1, CDKN1A, and IGF1, which are important regulatory molecules in the cancer misregulation pathway." (PMID 34120148, 2021). "Since IGF1 and BMR are highly correlated exposures, where IGF1 can affect BMR, we conducted multivariable MR to take into account the effect of GVs on cancer via IGF1 by adjusting for IGF1, and the results were consistent." (PMID 34567085, 2021). "Moreover, whether basal metabolic rate has a similar role in cancer for men and women independent of insulin-like growth factor 1 increasing cancer risk has not been investigated." (PMID 34567085, 2021). "CAF-derived soluble factors including IL6, IL17A, IGF1, IGF2, and nitric oxide indirectly can mediate the development of cancer treatment resistance." (PMID 32932015, 2021). "Our study showed that IGF-1 and IGF-1R harbor distinct prognostic values among different cancer types." (PMID 34804946, 2021). "However, it is not clear whether insulin and IGF-1 may promote cancer directly by promoting growth and preventing apoptosis, or by accelerating the aging process, which is a key risk factor for many cancers." (PMID 34572814, 2021). "The low expression of IGF-1 served as a favorable prognostic factor in some cancer types, including BLCA, CHOL, LAML, and UVM; whereas in SARC, high expression of IGF-1 served as a favorable prognostic factor." (PMID 34804946, 2021). "In this study, we analyzed the impact of IGF-1 and IGF-1R on the abundance of six immune infiltrates in cancers that harbor prognostic value, which are B cells, CD4+ cells, CD8+ cells, dendritic cells, macrophages, and neutrophils." (PMID 34804946, 2021). "In HCC, as in other types of cancer, VEGF shares common pathways with EGF, IGF-1, and HGF, such as MET, EKT, or Akt, among others." (PMID 34572344, 2021). "On the other hand, dairy products and especially milk are a dietary source of IGF-1, and evidence from laboratory studies suggests that overexpression of IGF-1 is involved in cancer pathogenesis through mitogenic and antiapoptotic effects." (PMID 33669972, 2021). "In the current study, we focused on the cancer signaling pathways, including TNF-α-induced NF-κB and IGF-1-induced PI3K/AKT and AMPK pathways." (PMID 34361052, 2021). "Lastly, we think that it exist the crosstalk between cancer cells and macrophages in muscle tissues, it is that tumor cells secrete IL-6 inducing macrophages to up-regulate MMP12 which degrade insulin and IGF-1 in muscle tissue." (PMID 34863141, 2021).
cancer (continued). "The correlation between the expression of IGF-1/IGF-1R and the immune infiltration levels across diverse cancer types is derived from TIMER." (PMID 34804946, 2021). "Thus, radio-resistance caused by GH and IGF1 is not conducive to radiotherapy for cancer." (PMID 34178997, 2021). "The activation of the fibroblast initiates the positive feedback loop, which secretes IGF1 and further activates IGF1R on cancer cells." (PMID 34360896, 2021). "IGF-1 encourages longitudinal bone growth, and both IGF-1 and IGF-2 take part in cancer progression." (PMID 34501405, 2021). "The role of IGFBP-1 as a transporter of IGF-1, and its RGD region, in activating integrin receptors in various cancer cells is well-known." (PMID 34531382, 2021). "They identified an increase in autocrine IGF1/AKT signaling in dormant cancer cells, and showed that pharmacological inhibition of IGF-1R reduces residual tumor and cancer recurrence." (PMID 35008235, 2021). "Other groups have illustrated that the expression of cancer stemness genes (OCT4, NANOG) induced by elevation of IGF-1/IGF-1R, correlates with high tumor recurrence in HCC patients and sorafenib resistance." (PMID 33669204, 2021). "The impact of high IGF-1 and IGF-1R on prognosis and immune infiltrates differs across cancer types." (PMID 34804946, 2021). "PF and especially FMDs, because of their periodic use, limited burden on human subjects, and effects on IGF-1, insulin, glucose, IGFBP-1 and ketone bodies levels, have the potential for applications in cancer prevention and treatment." (PMID 34572814, 2021). "Meanwhile, we confirmed the existence of 3 genes (COX-2, IGF-1 and WNT2) which are known to be subjected to miR-30a-3p regulation in human cancer cells based on previous studies 9, 19-21." (PMID 34093801, 2021). "The present work illustrated a comprehensive workflow for pan-cancer analysis and thoroughly investigated the role of IGF-1 and IGF-1R in cancers." (PMID 34804946, 2021). "In cancer, APP and APLP cleavage involve hormone insulin-like growth factor 1 (IGF-1), which is a well-known regulator of cell growth and cancer progression." (PMID 34066808, 2021). "As a result, CXCL10, IGF1, MMP3, MMP1, ICAM1, and IL-13 levels were markedly up-regulated within NPC samples relative to the non-carcinoma samples (P < 0.05)." (PMID 34544905, 2021). "More specifically, IGF-1 has recently been shown to mediate cancer cell survival through direct modulation of the PDK1 pathway, with enhanced phosphorylation of PDK1 observed following IGF-1 stimulation." (PMID 32228485, 2020). "IGF-1 secreted by activated PSCs and fibroblasts in PDAC stroma via IGF-1 receptor (IGF-1R) promote cancer cell migration, invasion and metastasis." (PMID 32660466, 2020). "An example of gene-specific methylation change includes the cancer cell-induced methylation and concomitant downregulation of the SOCS1 gene in PDAC CAFs, which enhanced cancer cell growth through the STAT3/IGF1 axis." (PMID 32760726, 2020). "Differential hydroxymethylation is found in thousands of genes, most significantly in genes related to pancreas development or function (GATA4, GATA6, PROX1, ONECUT1, MEIS2), and cancer pathogenesis (YAP1, TEAD1, PROX1, IGF1)." (PMID 33077732, 2020). "In TNBCs, stromal CAFs were identified as the source of IGF-1 and CXCL12, which were shown to prime cells to home the CXCL12- and the IGF1-rich bone microenvironment, in a process dependent on CXCR4 and IGF-1R expression by cancer cells." (PMID 33364239, 2020). "IGF-1 signaling plays a role in cancer tumorigenesis and metastasis, which led to the IGF1R becoming a therapeutic target for multiple cancer sites." (PMID 32226608, 2020). "Decreased IGF-1 levels reduce rates of malignancy and the inhibition of IGF-1R inhibits cancer growth." (PMID 33291663, 2020).
cancer (continued). "The insulin-, the IGF-1-, and the leptin-induced signaling cascades converge on activation of PI3K/AKT-mTOR pathway, which stimulates cancer cell proliferation and survival, the latter being also stimulated by the estrogen-induced CDK4/6." (PMID 33271979, 2020). "In this regard, we reviewed and compiled all of the published studies on GH, IGF-1, and both of their effects on ABC transporter expression in different cancers." (PMID 33291663, 2020). "Accordingly, inhibition of insulin, IGF-1, and leptin by fasting can co-operate with blockade of estrogen and CDK4/6 to abrogate cancer cell proliferation and survival." (PMID 33271979, 2020). "IGF-1 secreted by activated PSCs and CAFs via sonic hedgehog pathway activates IGF-1R in cancer cells triggering phosphorylation of insulin-receptor or Src substrates to promote PDAC metastasis via intracellular pathways such as RAS/MAPK." (PMID 32660466, 2020). "Our results indicate that polyploid ASC.B6 cells activate the pro-survival pathway in 4T1 cancer cells by changing the balance of their paracrine factors, namely, by downregulating IGFBP2 and secreting IGF1." (PMID 32133294, 2020). "QN15488 induces death in 32D/GR15 cells and many cancer cells including MCF-7 and HeLa cells via both IGF-1 dependent and independent manner." (PMID 33276615, 2020). "Blockade of the IGF1 pathway in ID8 cells with an IGF1 neutralizing antibody effectively inhibited the proliferation and migration of ID8 cancer cells." (PMID 33194645, 2020). "Therefore, metformin treatment-related decrease in circulating insulin levels correlates to the ‘indirect’ anti-cancer/anti-tumor effects of metformin via the inhibition of the mitogenic and pro-angiogenic signaling mechanisms which are otherwise activated by insulin and IGF1." (PMID 32883003, 2020). "The impact of resveratrol to reduce IGF-1 and IGFBP-3 in the blood indicated that the drug has an impact on cancer and the development of cancer." (PMID 32961987, 2020). "By computational analysis of the vast cancer genomics information in public databases (TCGA and METABRIC), we obtained evidence that high IGF-1 or IGF-1R levels correlate with a worse clinical outcome in TNBC patients." (PMID 32325700, 2020). "Especially, IGF1-activated PI3K/AKT/mTOR signaling pathway and inflammatory cytokines TNFα, IL6, and IL1α are closely related to muscle atrophy induced by cancer cachexia." (PMID 30922397, 2019). "Several cytokines were identified, including IL-6, IL-8, IGF1, IGF2, and CXCL12, all of which promoted survival of cancer cells." (PMID 31014370, 2019). "In osteoblastic metastases, osteoblasts produce many factors including insulin-like growth factor 1 (IGF-1), insulin-like growth factor 2 (IGF-2), TGF-β, TNF-α and IL-1β that act as chemoattractants for cancer cells." (PMID 30823602, 2019). "Calorie or glucose restriction (CR or GR) inhibits energy-dependent pathways, including IGF-1/PI3K/Akt/mTOR, in cancer cells." (PMID 31091659, 2019). "We focused on four well-established EMT-inducing agents, EGF, HGF, IGF-1, and TGF-β1, whose secretion by the cancer cells was higher than that by the PMCs." (PMID 31086083, 2019). "Elevated expression of IGF-1 and IGF-1R correlates with tumour progression, poor prognosis, apoptosis resistance and chemotherapy resistance in several cancer types, including BCa." (PMID 31076571, 2019). "The central gene is PIK3R1 in Module 0, which module contains eight DEGs related to classical cancer pathways (FCER1A, GNG11, IGF1, LIFR, PDK4, PIK3R1, RCAN2, and UGCG)." (PMID 31119098, 2019). "Every stimulation of cancer cell lines missing IR lead to down-regulation of DOK genes, whereas in control cell line with IR insulin or IGF1 stimulation resulted in up-regulation of DOK genes expression." (PMID 30929166, 2019). "In several human cancer cell lines, PP2A regulates Shc phosphorylation state and upregulates ERK signaling activity in the IGF1-induced signaling pathway." (PMID 31526479, 2019).
cancer (continued). "The niche of IL6 stimulates the expression of IGF-1R and autocrinal IGF1 dependently in HBV-HCCs and strongly correlates with OCT4/NANOG expression, early recurrence, and cancer stemness features." (PMID 31505803, 2019). "The crosstalk between CAFs and cancer cells activates RhoA/ROCK signaling in cancer cells, which is dependent on the secretion of IGF-1 by CAFs and PAI-1 upregulation in cancer cells." (PMID 29535813, 2018). "Conversely, IGF-1R expression decreases with cancer de-differentiation, suggesting that the IGF-2/IR-A loop exerts a more important role than the IGF-1/IGF-1R loop in thyroid cells de-differentiation, stemness, tumor progression, and metastasis." (PMID 30513575, 2018). "IGF-1/IGF-1R signaling is strongly dependent on nutrient availability and involves intensification of cancer cell proliferation, through the direct effects on PI3K/Akt signaling, and resistance to cell death imposed by chemotherapeutics and radiotherapy." (PMID 29868472, 2018). "In summary, we found that the crosstalk between CAFs and MDA-MB-231 BC cells increases the expression of IGF-1 in CAFs and PAI-1 activity in cancer cells." (PMID 29535813, 2018). "In MCF-7 and highly metastatic MDA-MB-231 human BC cells, stimulation with IGF-1 induces the overexpression of discoidin domain receptor 1 (DDR1), a collagen receptor tyrosine-kinase involved in EMT-dependent cancer progression." (PMID 30111747, 2018). "In the light of these findings, strategies able to attenuate, in cancer cells, the invasive and migratory potential related to IGF-1-mediated EMT induction, have a great potential in the prevention of cancer progression and metastasis." (PMID 30111747, 2018). "Growth factors stored in bone are released, including insulin growth factor-1 (IGF-1) and TGF-beta, which are used by cancer cells to produce additional PTHrP." (PMID 29867053, 2018). "Activated osteoblasts then produce increased amounts of growth factors including VEGF, IGF-1, and TGF-beta, which support cancer cell growth and proliferation." (PMID 29867053, 2018). "Several studies have revealed altered expression of Insulin-like Growth Factor-1 (IGF-1) and its receptor (IGF-1R) in different types of human cancers, particularly in NETs." (PMID 29854305, 2018). "Both IGF1 and PAI-1 activate RhoA/ROCK signaling in cancer cells, which increases cell scattering and invasion." (PMID 29535813, 2018). "In other cancer contexts, Cbl proto-oncogene C (CBLC) combines with IGF-1R and mediates receptor polyubiquitination in response to IGF-1." (PMID 30111747, 2018). "Under the influence of CAF-secreted IGF1 and SDF-1 (stromal-derived factor-1) a subpopulation of cancer cells that expressed the IGF1 receptor IGF1R and the SDF-1 receptor CXCR4 outgrew other cancer cell subpopulations." (PMID 29774124, 2018). "In a transwell co-culture system (where CAFs and cancer cells were physically separated), MDA-MB-231 cells increased the transcription of IGF1 by 12 fold in CAFs." (PMID 29535813, 2018). "In cancer cells, 1,25(OH)2D/VDR activates cyclin-dependent kinase inhibitors (e.g., p21, p27), inhibits mitogenic growth factors such IGF-1 and EGF, and promotes the activity of TGF-β, thus inhibiting cell proliferation and cancer growth." (PMID 29951549, 2018). "IGF-1 is a strong mitogen, which stimulates IGF-1R signaling and thus plays important roles in the occurrence and growth of several cancers." (PMID 30213025, 2018). "IGF-1, as well as insulin, activates the MAPK pathway and the PI3K pathway, which are both involved in cancer development and progression." (PMID 30363988, 2018). "The increased expression of both IGF-1 and PAI-1 enhances RhoA signaling in cancer cells, which promotes cell scattering and invasion." (PMID 29535813, 2018). "Binding of insulin-like growth factor-I (IGF-1) to its receptor (IGF-1R) initiates downstream signals that activate PI3K/Akt/mTOR and MEK/Erk pathways, which stimulate cancer cell proliferation and induce drug resistance." (PMID 29843755, 2018).
cancer (continued). "A growing body of evidence indicates that the IGF-1/IGF-1R signaling pathway is a key player in BC cell therapy resistance and cancer recurrence." (PMID 30111747, 2018). "Two distinct mechanisms induced the activation of the RhoA/ROCK pathway in MDA-MB-231 cells, the secretion of IGF-1 by CAFs and the upregulation of PAI-1 in cancer cells." (PMID 29535813, 2018). "IGF-1 signaling is the main EMT axis in GC and, in general, it follows RAS/MEK/ERK and PI3K/AKT routes, which are common to other types of cancer." (PMID 30111747, 2018). "On the other hand, the IGFBP3 is known to bind IGF1 as well as IGF2 and have an anti-tumor effect in several types of cancers and its concentration decreases markedly in circulation of cancer patients." (PMID 28223541, 2017). "Mesenchyme-derived growth factors known to promote cancer cell proliferation (EGF, FGF1, FGF2, and IGF-1) were expressed in different CAF populations to different levels." (PMID 28649646, 2017). "The sensitivity of cancer cells to growth factors: EGF and IGF-1 alone and in combination, was evaluated following tunicamycin treatment and the role of glycosylation on sensitivity to DXR was determined." (PMID 28223691, 2017). "Our previous studies suggested that α6β4, another integrin that is overexpressed in cancer cells, is critically involved in IGF1/IGF1R signaling through direct binding to IGF1." (PMID 28873464, 2017). "Previously, ERK1/2 and AKT signaling cascades have emerged as pivotal transduction mediators involved in IGF1-induced and HIF-1-dependent responses in cancer cells." (PMID 29212519, 2017). "NDUFA4L2 and its binding partners participated in growth and death processes and multiple cancer-related KEGG pathways, such as the IGF-1, mTOR (Populo, Lopes & Soares, 2012) and PI3K/AKT signaling pathways." (PMID 29158991, 2017). "Overexpression of α-Klotho or treatment with sKl inhibits insulin/IGF-1-mediated downstream effectors IRS-1, Akt1, and ERK1/2 in cancer cells." (PMID 29250031, 2017). "We also detected upregulation of genes involved in cancer metastasis and cancer stemness (FOXC2, SNAI2, CXCRs, and IGF1), cell stemness (NANOG, POU5F1, and KLF4), metalloproteinases (MMP7, MMP10, and MMP13), and angiogenic factors (IL-8 and S1PR1)." (PMID 28423353, 2017). "Cancer cells utilize the IGF-1 signaling pathway to redirect their metabolic investment towards proliferation and growth, and thus reduction of IGF-1 levels in CR results in decreased tumor growth and progression." (PMID 28539118, 2017). "Scatter plot of genes array data showed that LP-4 up-regulated the Igf1, Fam176a, Ulk-1, PERK, Cxcr4, and Sqstm1 (p62) genes in HeLa cancer cells." (PMID 28670281, 2017). "During mitogenesis, IGF-1 exerts its function through cell signaling networks resulting in the activation of both IGF-1-dependent MAPK-proliferation and PI3K-anti-apoptosis pathways for cancer promotion." (PMID 27509024, 2016). "More studies are needed to understand the biological implications of these metabolic adaptations on cancer risk, health, and longevity, and whether or not other nutritional interventions (e.g., protein restriction or intermittent fasting) reduce serum IGF1 concentration in humans." (PMID 26443692, 2016). "IGF1 and RXRA are both involved in a pathway named “Pathways in cancer” which is known to be related to CAD." (PMID 27835645, 2016). "The effects of CAFs, IGF1, and IGF1R inhibitors on the motility of cancer cells were examined by wound-healing assay or invasion assay under normoxia (20% O2) and hypoxia (1% O2)." (PMID 27487118, 2016). "Mmu-miR-505-5p was downregulated in Sca-1+CD31− compared to Sca-1+CD31+ cells, with targets Cyp1b1, Dcbld2, Igf1, and Ppp1r14b,Txndc5 increased in expression; Igf1 was involved in mTOR and PI3K-Akt signaling and Cyp1b1by with microRNAs in cancer." (PMID 27298624, 2016).